ERG (ETS transcription factor ERG)
Diseases named in the same sentence as ERG in open-access papers (continued):
Sharing a sentence is not in itself a finding about the gene and the disease.
tumor (continued). "Interestingly, in multivariate logistic regression analyses, only TMPRSS2:ERG added significant predictive value to the ERSPC-RC to predict biopsy Gleason score (OR, 7.16; P < 0.001) and clinical tumor stage (OR, 2.60; P = 0.023), whereas PCA3 did not." (PMID 26339615, 2015). "Since the worst prognosis was found for PTEN-deleted and ERG-positive tumors that completely lacked any detectably SOX9 expression, SOX9 might even impair tumor growth in this specific molecular background." (PMID 26030748, 2015). "In addition, tumour tissue from patient #3 displayed higher PIM1 and ERG levels than the corresponding autologous non-malignant prostate." (PMID 22140532, 2011). "Additionally, the tumor was negative for most immunohistochemical markers (CKAE1/AE3, p63, CD23, CD21, MUC4, NUT, CDK4, Pan-TRK, STAT6, SS18, MDM2, Desmin, S100, ERG, TLE1, Fli) and showed only weak and most probably unspecific expression of CD99, CD56, and CD34." (PMID 39519042, 2024). "(Immunohistochemical stains showed that the tumor cells were positive for desmin and TFE3, while negative for pancytokeratin, CAM5.2, EMA, chromogranin, synaptophysin, NSE, CD45, SMA, HHF35, myogenin, CD117, DOG1, MUC4, S100, SOX10, HMB45, Melan-A, CD31, ERG, TLE1, STAT6, and Cathepsin-K)." (PMID 35001360, 2022).
cancer (403 papers, 2007 to 2026). A tumor composed of atypical neoplastic, often pleomorphic cells that invade other tissues. "The authors developed O’PROTACs targeting lymphoid enhancer-binding factor 1 (LEF1) and the ETS-related gene (ERG), two transcription factors highly implicated in cancer." (PMID 40507351, 2025). "In ERG positive cancers, low MTAP expression was associated with deletions of PTEN (p = 0.0002), 12p13 (p < 0.0001), and 18q21 (p = 0.0006)." (PMID 40554389, 2025). "Aggressive carcinomas develop only in the presence of additional mutations, such as abnormal expression of ERG, loss of IL-6/STAT3 functionality, dysfunction of the methyltransferase Kmt2c or activation of the RAS/MAPK cascade." (PMID 38811984, 2024). "In general, PTEN loss is also linked to aggressive cancer phenotype, and ERG gain cancers with loss of PTEN lead to the worst disease outcomes." (PMID 37345203, 2023). "The results showed that higher ERG scores were associated with enhanced drug resistance of cancer cell lines to WEHI‐539 and BMS‐345541." (PMID 37102261, 2023). "The most probable mechanism that has been proposed for the role of ERG in cancer is linked to the formation of gene fusion of TMPRSS2 and ERG." (PMID 37762215, 2023). "One option is the MyProstateScore (MPS) test (LynxDx, Inc., Ann Arbor, MI), which combines urinary expression of prostate cancer antigen 3 (PCA3) and the TMPRSS2:ERG gene fusion (T2:ERG) with serum PSA to define the risk of GG ≥ 2 cancer." (PMID 36585434, 2023). "Researchers have begun to elucidate the role of ERG in the oncogenic mechanisms associated with tumorigenesis and cancer progression in their search for potential non-invasive biomarkers and novel targeted therapeutics." (PMID 35563163, 2022). "It showed that PITX1 positivity was strongly linked to all four deletions (p < 0.0001 each) in ERG-negative cancers, while this association was lost in ERG-positive cancers, most likely because of the general upregulation of PITX1 in this subset." (PMID 35267575, 2022). "Our data show that BRD9 mutations are less prevalent in ERG fusion positive cancers, in line with the literature suggesting these cancers are less likely to have mutated SWI/SNF complexes." (PMID 34944438, 2021). "Taken with PARP1 involvement in regulating AR transcriptional activity, the loss of PARP1 in ERG fusion positive cancers would disrupt ERG expression and transcriptional activity." (PMID 34208794, 2021). "Compared to PZ cancer cases, TZ cancer cases showed an extremely lower prevalence of ERG‐overexpression (3.2% vs 20.1%) and PTEN‐loss (2.2% vs 18.2%) with a significant difference (P = .0001 and <.0001, respectively)." (PMID 35475132, 2021). "Previous studies indicated that ERG cannot promote cancer by itself, but that ERG works together with mutations that activate the protein AKT." (PMID 34314419, 2021). "We outline the involvement of tubulin alterations, androgen receptor (AR) signaling/AR variants, ERG rearrangements, drug efflux/influx, cancer stem cells, centrosome clustering, and phosphoinositide 3-kinase/AKT signaling in mediating DTX resistance." (PMID 35582222, 2020). "In ERG-positive cancers, an unequivocal association was only found between SFRP4 up regulation and positive surgical margin (p = 0.0104) but not with any other histological parameter nor with patient prognosis." (PMID 32677026, 2020). "High cytoplasmic and nuclear YAP1 were both significantly linked to cancers with TMPRSS2:ERG rearrangement and ERG expression." (PMID 32488048, 2020). "This association was much less strong in ERG positive cancers where it only reached statistical significance for 3p14, and 12p13, and 16q24." (PMID 32143573, 2020). "It was, thus, not surprising that the ERG-associated hnRNPA1 was linked positively to ERG-associated deletions but inversely to those deletions that prevail in ERG-negative cancers." (PMID 32417965, 2020).
cancer (continued). "We next wanted to test the ability of Hit B to inhibit known ERG-EWS-mediated cancer-associated phenotypes." (PMID 32915889, 2020). "Subset analyses revealed that this association was true for both ERG‐negative and ERG‐positive cancers (P < 0.0001)." (PMID 31736271, 2020). "While p16 expression in cancer tissues is similar in AA and EA PCa tissues, p16 expression is more strongly associated with ERG expression in AA men and is associated with increased p16 expression in benign tissues." (PMID 31111520, 2019). "In ERG positive cancers, this association reached statistical significance only for PTEN (p<0.0001)." (PMID 31557128, 2019). "In ERG-negative cancer, high levels of BCAR1 expression were significantly linked to presence of deletions of PTEN (p < 0.0001), CHD1 (5q21) (p < 0.0001) and MAP3K7 (6q15) (p < 0.0001), while these associations were lost in ERG-positive cancer." (PMID 29304771, 2018). "Subset analyses of ERG-positive and ERG-negative cancers revealed that these associations were largely driven by the subset of ERG-negative cancers (p < 0.0001 each)." (PMID 28515422, 2017). "Phenotypic biological assays indicate that restoring the expression of miR-449a (by over-expression) or miR-874 (by suppression) can rescue the invasive cancer phenotype of the ERG-associated CaP cells." (PMID 26988912, 2016). "In this study we examined potential associations between TMPRSS2:ERG gene fusion and clinicopathological characteristics with the aim of helping predict the cancer outcome." (PMID 27377958, 2016). "Deletions at 3p13 and 10q23 (PTEN) are associated with ERG-positive cancers, while 5q21 and 6q15 are inked to ERG-negative cancers." (PMID 25825985, 2015). "PTEN deletions were positively associated with SOX9 expression in ERG-negative (p<0.0001) but inversely linked to SOX9 expression in ERG-positive cancers (p<0.0001)." (PMID 26030748, 2015). "All of the stromal changes that were found to associate with epithelial ERG expression are related to more aggressive cancer." (PMID 24505269, 2014). "In total, for the first time, we reported that ERG rearrangement was associated with cancer-related death in Chinese PCa patients." (PMID 24516518, 2014). "In summary, we reported that ERG rearrangement was associated with cancer-related death in Chinese PCa patients." (PMID 24516518, 2014). "This genomic region encompasses upstream regulatory elements (-13.5 kb) shown to control cancer-associated expression of the ERG oncogene." (PMID 24418414, 2014). "In the case of TMPRSS:ERG, its major drawback as a diagnostic marker is its rather heterogeneous occurrence in cancer patients of different ethnic groups." (PMID 25237833, 2014). "As we move toward describing CaP by molecular alterations, use of ERG typing (and other potential cancer genes) for diagnostic and therapeutic roles has the potential to help unravel the biologic differences in CaP across ethnic groups." (PMID 23892597, 2013). "Ectopic expression of the most frequent fusion partner, ERG (v-ets erythroblastosis virus E26 oncogene homolog, avian), promotes multiple signaling pathways associated with cancer formation and progression." (PMID 22202492, 2011). "Despite the lack of characterisation of the individual proteins, the phenotypic features of the TMPRSS2:ERG-associated cancers, as a class, have been described." (PMID 18781147, 2008). "Several early cohort studies suggest that the presence of the TMPRSS2:ERG fusion product is associated with relatively poor cancer-specific survival." (PMID 18781147, 2008). "It has been shown that soluble guanylyl cyclase (sGC) is strongly associated with the TMPRSS2-ERG fusion in clinical PCa cohorts and that the sGC-mediated NO-cGMP pathway is a critical downstream effector of ERG in promoting cancer cell proliferation and tumorigenesis." (PMID 36769153, 2023).
cancer (continued). "While ERG has been implicated in regulation of variety of cancer-relevant signal transduction pathways, the exact mechanism that is responsible for its role in PC initiation is still unknown and it will likely remain the subject of active investigation." (PMID 37973913, 2023). "Many ETSs have been associated with cancer, such as ERG (ETS-Related Gene), through gene fusion." (PMID 35361282, 2022). "The TZ cancer cases showed a significantly lower prevalence of ERG‐overexpression and PTEN‐loss." (PMID 35475132, 2021). "Additionally, TZ cancer cases showed a significantly lower prevalence of ERG‐overexpression and PTEN‐loss than PZ cancer cases (3.2% vs 20.1% and 2.2% vs 18.2%, respectively)." (PMID 35475132, 2021). "However, gene expression signatures of PCa with SPOP mutations and TMPRSS2:ERG fusions appeared to be similar, leading to the inference that increased ERG activity was a main oncogenic driver in cancers with SPOP mutations." (PMID 34066106, 2021). "We hypothesized that down-regulated miR-200b-3p in HCC may cause enhanced endothelial ERG expression, leading to increased angiogenesis in the cancer microenvironment." (PMID 32591615, 2020). "Additionally, we demonstrate that HCC tissues exhibit reduced miR-200b-3p expression, which causes augmented endothelial ERG expression, promoting angiogenesis in the cancer microenvironment." (PMID 32591615, 2020). "This association held true in the subset of ERG positive cancers (p ≤ 0.02)." (PMID 33195694, 2020). "However, subset analyses revealed that hnRNPA1 overexpression was associated with 9 of 11 deletions in ERG-negative cancers (p < 0.05) and with 6 of 11 deletions in ERG-positive cancers (p < 0.05)." (PMID 32417965, 2020). "Alternatively, this may be due to experimental issues caused by the general ROCK1 up-regulation in ERG positive cancers." (PMID 31557128, 2019). "The observed up-regulation of nuclear ELAC2 expression in the subset of ERG positive cancers might be caused by a general up-regulation of the TGF-ß pathway as a consequence of ERG fusion." (PMID 31452838, 2019). "Subset analysis of ERG-negative and ERG-positive cancer revealed that these associations were largely driven by the subset of ERG-negative cancers, while most differences were only small in ERG-positive cancers." (PMID 29304771, 2018). "CYP26A1 is a methylation marker of PCs associated with ERG-positive cancers." (PMID 28651018, 2017). "These will ultimately help identify novel anti-cancer therapeutic targets for ERG-associated CaP." (PMID 26988912, 2016). "However, separate analyses of ERG-positive and ERG-negative cancers revealed that this association was solely driven by the subset of ERG-positive cancers." (PMID 26030748, 2015). "TMPRSS2:ERG score was also significantly higher in men with high prostatectomy Gleason score (>6 versus 6) (P = 0.009) and was significantly associated with Gleason score upgrading and significant cancer (P = 0.008 and P = 0.004, resp)." (PMID 26339615, 2015). "We found that ERG is highly associated with death and aggressive cancer." (PMID 22811706, 2012). "PTEN loss has been associated with ERG rearrangement and adverse clinical course including post-PR upgrading, biochemical recurrence, progression after adjuvant treatment, as well as cancer-specific death in both hormone-naïve/hormone-sensitive, and castration-resistant patients." (PMID 34884287, 2021). "Interestingly, we found that ROCK1 up-regulation was linked to higher patient age exclusively in cancers harboring the ERG fusion, suggesting that the consequences of ERG fusion may vary with age." (PMID 31557128, 2019). "Furthermore, ERG regulates the expression of target genes associated with cancer initiation and progression pathways such as DNA damage, inflammation, epigenetic control, regulation of differentiation, epithelial mesenchymal transition (EMT), cell proliferation and cell invasion." (PMID 29299133, 2017).
cancer (continued). "This study was designed to systematically locate the regions of differential expression of these genes in single cross-sections of five cancerous prostates and evaluate whether the location of the carcinoma was associated with TMPRSS2-ERG or PCA3 mRNA levels or ERG protein expression." (PMID 26294063, 2015). "Notably, the functional annotation analysis indicated that similar consequences on the cancer transcriptome derived from the over-expression of ERG and loss of ESE3 and that these two ETS factors probably could act in part through common molecular pathways." (PMID 20479932, 2010). "In concordance with observations in human AS, the dog tissues demonstrated specific and abundant overexpression of ERG in the vast majority of cancer cells." (PMID 41009669, 2025). "Consistent with a context-specific role in lymphoid malignancies, analysis of genome-scale CRISPR screening data from the Cancer Dependency Map showed that ERG dependency is enriched in lymphoid lineages compared to other cancer types." (PMID 41509392, 2025). "In ERG positive cancers, MTAP expression decreased with advanced pT stage (p < 0.0001), classical (p = 0.0004) and quantitative Gleason grade (p = 0.0005), and low MTAP expression was significantly linked to early PSA recurrence (p = 0.0012)." (PMID 40554389, 2025). "As expected, large clusters of ERG+ luminal cancer cells are present in the ERG+ patients in both datasets, but we also observed rare ERG+ cells in the corresponding basal clusters of these same patients." (PMID 40858905, 2025). "Yoshimoto and colleagues, in a small set of cases, observed that cancers with both ERG rearrangements and PTEN deletions had the worst prognosis." (PMID 40427154, 2025). "Collectively, ERG-driven cancers initiate in basal cells, which expand initially as highly proliferative IM cells then transition to luminal cells that typify human PCa." (PMID 40858905, 2025). "This was based on morning first catch (non-DRE) urine and generated the following AUCs for the presence of any cancer: ERG 0.782, PCA3 0.783, PSMA 0.772, CK19 0.731, EpCAM 0.739." (PMID 38730670, 2024). "Although FOXA1 and MYC had a less significant correlation with integrin genes, ERG showed an overwhelmingly positive correlation with them in pan-cancer, pointing ERG as an essential upstream TF of integrins." (PMID 39436262, 2024). "Among these genes, we can find some encoding cancer-relevant transcription factors such as E2F1 CTCF, and ERG and DNA methyltransferase enzymes (DNMT1)." (PMID 38773638, 2024). "In 21q22, we detected amplification of five cancer genes, including the transcription factors ERG and RUNX1 and the RNA binding protein U2AF1." (PMID 39421445, 2024). "This gene rearrangement is evident in approximately 50% PCa patients, leading to overexpression of the oncogene ERG and subsequently enhanced proliferation and many hallmarks of cancer." (PMID 37752916, 2023). "Our data identify the PSAP protein as ERG-dependent, with higher expression levels in ERG-negative than in ERG-positive cancers." (PMID 37892063, 2023). "Even though ERG was found to regulate multiple cancer relevant signaling pathways, the exact mechanism responsible for ERG-meditated oncogenic transformation at the time of human PC initiation is still not clear." (PMID 37973913, 2023). "Well‐known cancer critical genes like BRCA1, IDH1, ERG, KMT2C, MSH6 and PALB2 were among the mutated genes in the metastatic samples." (PMID 35880692, 2023). "In our PB-Cre4/Ptenfl/fl/ERG/Snd1fl/fl model of PC the cancer-driving Pten inactivation co-occurs with deletion of Snd1, as both of these events are carried out by same Cre recombinase." (PMID 37973913, 2023).